LRRD1 (leucine rich repeats and death domain containing 1)
Synonyms: IMAGE:4798971
Tractability: No criterion of Open Targets' tractability assessment is met for any kind of drug.
Gene: Protein-coding gene on chromosome 7 (92,141,643 to 92,179,531, reverse strand). Ensembl gene ENSG00000240720.
Gene Ontology:
Biological process: signal transduction
Cellular component: cytoplasm
Genetic constraint (gnomAD): Loss-of-function variants: 37 observed, 50.35 expected, observed/expected ratio (o/e) 0.73, 90% interval 0.56 to 0.97. The upper end of that interval is the gene's LOEUF score, 0.97, which puts it in group 4 of 6, group 1 being the genes least tolerant of losing a copy. Missense variants: 662 observed, 793.49 expected, observed/expected ratio (o/e) 0.83, 90% interval 0.78 to 0.89. Synonymous variants: 252 observed, 286.29 expected, observed/expected ratio (o/e) 0.88, 90% interval 0.79 to 0.98.
Homologues: Orthologues: chimpanzee LRRD1 (99% identical), macaque LRRD1 (97% identical), dog LRRD1 (80% identical), pig LRRD1 (79% identical), rabbit LRRD1 (77% identical), guinea pig LRRD1 (75% identical), rat Lrrd1 (66% identical), mouse Lrrd1 (66% identical), tropical clawed frog lrrd1 (39% identical). Paralogues in human: ERBIN (20% identical), SCRIB (20% identical), LRRC7 (18% identical), PHLPP2 (17% identical), PHLPP1 (17% identical), LRRIQ4 (16% identical), LRRC40 (16% identical), SHOC2 (16% identical), LRRC1 (15% identical), MFHAS1 (15% identical), LRRC8A (14% identical), LRRC8B (14% identical), and 19 more.
Diseases named in the same sentence as LRRD1 in open-access papers:
LRRD1 is named in the same sentence as 1 disease in open-access papers, as found by Europe PMC text mining. Sharing a sentence is not in itself a finding about the gene and the disease. The quoted sentences say what the papers report.
multiple sclerosis (1 paper, 2021). A progressive autoimmune disorder affecting the central nervous system resulting in demyelination. "The two-way analysis to identify genes differentially expressed in CSF versus bloodin multiple sclerosis versus non-inflammatory controls yielded four significantgenes: LRRD1, CYP51A1, PASK andYes1." (PMID 34761221, 2021).